DCXR (dicarbonyl and L-xylulose reductase)
Description:
Catalyzes the NADPH-dependent reduction of several pentoses, tetroses, trioses, alpha-dicarbonyl compounds and L-xylulose. Can use both NAD and NADP as cosubstrate but shows higher activity with NADP. Participates in the uronate cycle of glucose metabolism. May play a role in the water absorption and cellular osmoregulation in the proximal renal tubules by producing xylitol, an osmolyte, thereby preventing osmolytic stress from occurring in the renal tubules.
Synonyms: XR; kiDCR; SDR20C1; DCR; HCR2; P34H; HCRII; PNTSU
Tractability: Small molecule: a structure with a bound ligand is known; it has a high-quality binding pocket. Antibody: its Gene Ontology location is reachable by antibodies, with high confidence; UniProt places it where antibodies can reach, with medium confidence. PROTAC: ubiquitination databases record sites on it; its protein half-life has been measured.
Target class: Enzyme; Oxidoreductase
Gene: Protein-coding gene on chromosome 17 (82,035,136 to 82,037,776, reverse strand). Ensembl gene ENSG00000169738.
Subcellular location: Apical cell membrane; Cytoplasmic vesicle, secretory vesicle, acrosome
Subcellular location (Human Protein Atlas): Microtubules
Pathways (Reactome):
Disease: Essential pentosuria
Metabolism: Formation of xylulose-5-phosphate
Gene Ontology:
Molecular function: identical protein binding; L-xylulose reductase (NADPH) activity; oxidoreductase activity, acting on NAD(P)H, quinone or similar compound as acceptor; protein binding; carbonyl reductase (NADPH) activity; oxidoreductase activity, acting on CH-OH group of donors
Biological process: glucose metabolic process; positive regulation of reactive oxygen species metabolic process; xylulose metabolic process
Cellular component: cytoplasmic microtubule; extracellular exosome; mitochondrion; nucleus; plasma membrane; acrosomal vesicle; apical plasma membrane; brush border; cytosol; microvillus
Genetic constraint (gnomAD): Loss-of-function variants: 28 observed, 28.19 expected, observed/expected ratio (o/e) 0.99, 90% interval 0.74 to 1.36. The upper end of that interval is the gene's LOEUF score, 1.36, which puts it in group 5 of 6, group 1 being the genes least tolerant of losing a copy. Missense variants: 348 observed, 323.12 expected, observed/expected ratio (o/e) 1.08, 90% interval 0.99 to 1.18. Synonymous variants: 161 observed, 135.15 expected, observed/expected ratio (o/e) 1.19, 90% interval 1.05 to 1.36.
Homologues: Orthologues: chimpanzee DCXR (98% identical), macaque DCXR (95% identical), guinea pig DCXR (84% identical), mouse Dcxr (84% identical), zebrafish dcxr (68% identical), pig CBR2 (68% identical), tropical clawed frog dcxr (68% identical), Caenorhabditis elegans dhs-21 (48% identical), Drosophila melanogaster CG7322 (46% identical).
Diseases named in the same sentence as DCXR in open-access papers:
DCXR is named in the same sentence as 29 diseases in open-access papers, as found by Europe PMC text mining. Sharing a sentence is not in itself a finding about the gene and the disease. The quoted sentences say what the papers report.
chronic kidney disease (2 papers, 2025). Impairment of the renal function secondary to chronic kidney damage persisting for three or more months. "DCXR expression was down-regulated in glomerular tissue of chronic kidney disease, which was negatively correlated with disease severity and lead to poor outcome." (PMID 40460381, 2025). "The DCXR presented the protective factor in chronic kidney diseases for its function of dicarbonyls clearance." (PMID 40919435, 2025). "DCXR was a renal protective factor in chronic kidney disease." (PMID 40460381, 2025).
diabetes (2 papers, 2024). "In the SOY1.5 group, the hub gene of the Darkturquoise module, DCXR, acts as an enzyme mediating the reductive metabolism of toxic reactive and toxic carbonyl compounds, already associated with diseases such as diabetes." (PMID 39021677, 2024). "Among the diabetes-associated plasma proteins, only those encoded by COMT and DCXR showed a potential causal effect with T2DM complications (p < 0.05)." (PMID 39280009, 2024).
Arthritis (1 paper, 2025). Inflammation of a joint. "One previous confirmed that DCXR can promote Th2 cell differentiation, inhibit the release of inflammatory factors, and delay the progression of arthritis." (PMID 40460381, 2025).
breast carcinoma (1 paper, 2025). "DCXR has been reported to promote the proliferation and cell cycle progression of breast cancer by promoting glycolysis activity." (PMID 40919435, 2025).
congenital cataracts (1 paper, 2022). "The study indicates that DCXR functions in fluid homeostasis by regulating cellular osmolality in C. elegans and provides insights into DCXR-involved clinical conditions, such as congenital cataracts and malfunctioning lung and kidney." (PMID 36275448, 2022).
follicular adenoma (1 paper, 2024). "Comparative proteomics analysis using a high-performance liquid chromatography-tandem mass spectrometry approach revealed TSPAN30, DDB1, TYMP, VDAC2, and DCXR as the top five candidate biomarkers for directly comparing samples of follicular adenoma and normal thyroid tissue." (PMID 38649381, 2024).
glioma (1 paper, 2021). A benign or malignant brain and spinal cord tumor that arises from glial cells (astrocytes, oligodendrocytes, ependymal cells). "The present study was novel in building a uronic acid metabolic process–related signature involving five genes (UGT8, DCXR, SORD, XYLB, and CRYL1) to predict the survival of glioma in the CGGA database." (PMID 33324981, 2021).
liver cancer (1 paper, 2025). An epithelial or non-epithelial malignant neoplasm that arises from the liver. "Another study indicated that DCXR was specifically expressed in liver and kidney tissue and was a potential biological marker of liver cancer." (PMID 40460381, 2025).
melanoma (1 paper, 2015). A malignant, usually aggressive tumor composed of atypical, neoplastic melanocytes. "It has been reported that the DCXR protein can be found in the nuclear compartment of cells with increased expression of the protein in melanomas." (PMID 25815750, 2015).
nephritis (1 paper, 2022). Inflammation of renal tissue. "The transgenic mice overexpressing DCXR accumulate less dicarbonyls (DCs) under surgically-induced carbonyl stress that causes nephritis, while DCXR knock-out mice are more vulnerable to protein damage in diacetyl-induced cytotoxicity." (PMID 36275448, 2022).
Nephropathy (1 paper, 2024). A nonspecific term referring to disease or damage of the kidneys. "DCXR was found to be causally associated with T2DM nephropathy, yet the causal direction was inconsistent with T2DM, suggesting potential bias." (PMID 39280009, 2024).
neuropathy (1 paper, 2024). A disorder affecting the nervous system that manifests with pain, tingling, numbness, and/or muscle weakness. "In the tibial nerve, increased expression of DCXR, GCDH, and TUFM was identified as risk factors for T2DM neuropathy." (PMID 39280009, 2024).
Obesity (1 paper, 2024). Accumulation of substantial excess body fat. "Four differentially expressed genes (ESR1, GCDH, FAHD2A, DCXR) were common in obesity and HCC." (PMID 38977823, 2024). "In the present study, we have identified four differentially expressed genes shared between obesity and HCC, namely ESR1, GCDH, FAHD2A, and DCXR." (PMID 38977823, 2024). "Four differentially expressed genes, including ESR1, GCDH, FAHD2A, and DCXR, were found to overlap between HCC and obesity." (PMID 38977823, 2024).
pentosuria (1 paper, 2022). Pentosuria is an inborn error of metabolism which is characterized by the excretion of 1 to 4 g of the pentose L-xylulose in the urine per day. "A person with pentosuria caused by DCXR deficiency excretes about 2∼4 g of L-xylulose." (PMID 36275448, 2022).
prostate carcinoma (1 paper, 2025). A carcinoma that arises from epithelial cells of the prostate gland. "While DCXR is known to be upregulated in prostate cancer and expressed at low levels in normal prostate epithelial cells, its role in BPH has not been extensively explored." (PMID 40919435, 2025).
tumor (7 papers, 2015 to 2026). "Recent observations associate DCXR with a role in cell adhesion, pointing to a novel function involving tumor progression and possibly metastasis." (PMID 33324981, 2021). "Protein profiling identified ITH-associated proteins (WDR5, CKB, IPO11, ATP6V1F, DCXR and PCCB) and underscored pathway variations including tumour suppressor and proto-oncogenic signalling, vascularization and metabolic regulation." (PMID 41580526, 2026). "DepMap demonstrated that the deletion of UBC, DARS2, and DCXR significantly inhibited tumor cell proliferation, asserting their roles in maintaining tumor growth." (PMID 39990673, 2025). "Notably, radiation induced upregulation of AK1 and DCXR, regulatory factors known to enhance glycolysis in microglia and tumor cells, an effect that was mitigated following microglia replenishment." (PMID 40390112, 2025). "Recent observations suggest that DCXR may have a role in cell adhesion, potentially contributing to tumor progression and metastasis." (PMID 37754259, 2023).
cancer (5 papers, 2018 to 2025). A tumor composed of atypical neoplastic, often pleomorphic cells that invade other tissues. "Irradiated PP2 and COMP-treated A549 cells exhibited lower protein concentration of DCXR, a protein associated with increased proliferation and progression of various cancer types." (PMID 40141111, 2025). "The deficiency of DCXR may be associated with a DM and cancer." (PMID 40460381, 2025). "Similarly, DCXR involves in xylulose metabolism and plays a crucial role in maintaining glycolytic capacity and cancer cell proliferation." (PMID 40390112, 2025).
respiratory diseases (1 paper, 2020). "Reactive carbonyls are known to cause severe respiratory diseases, which are detoxified by carbonyl reductases in the lung, in particular, DCXR that mediates chemical redox cycling." (PMID 32788598, 2020).
DCXR also shares sentences with these, for which no sentence is quoted: autoimmune disease (3 papers); metabolic syndrome (2); ependymoma (1); lung carcinoma (1); lupus-like syndromes (1); minimal change disease (1); prostatitis (1); rhabdomyolysis (1); systemic lupus erythematosus (1); thrombotic microangiopathy (1); virus infection (1).